BMP6 (bone morphogenetic protein 6)
Diseases named in the same sentence as BMP6 in open-access papers (continued):
Sharing a sentence is not in itself a finding about the gene and the disease.
anemia (continued). "On the other hand, the analysis of the BMP-6 concentration showed that it is significantly higher in patients with CD and anemia compared to the control group." (PMID 37755286, 2023). "The aim of the presented study is to analyze the concentration of erythroferrone and BMP-6 in IBD patients with concomitant anemia in relation to clinical and laboratory data in the study group." (PMID 37755286, 2023). "ACVR1 plays an important role in hematopoiesis and anemia via the BMP6/ACVR1/SMAD pathway, which regulates expression of hepcidin, the master regulator of iron homeostasis." (PMID 38201581, 2023). "IRIDA is one type of iron-deficiency anemia due to mutation of the transmembrane serine protease 6, which cleaves HJV and, in turn, inhibits BMP-6-induced hepcidin expression." (PMID 34679725, 2021). "Eli Lilly and Company developed LY3113593, a monoclonal humanized antibody against BMP6, for the treatment of anemia in patients with CKD." (PMID 30469435, 2018). "In the severe anemia group, a down-regulation of bmp6 and fth was also observed, at days 14 and 7, respectively." (PMID 27100629, 2016). "We therefore predicted that factors other than anemia and Epo regulate Bmp6 expression in these mice." (PMID 24454764, 2014). "On the other hand, when analyzing the differences in BMP-6 concentration in the studied groups of patients, significantly higher BMP-6 levels were found in patients with CD with concomitant anemia compared to the control group (0.432 ± 0.158 ng/mL vs. 0.359 ± 0.072 ng/mL, p = 0.021)." (PMID 37755286, 2023). "Thus, treatment with these drugs improved anemia in a heat-killed Brucella abortus mouse model of AI, and even further suppressed hepcidin in Bmp6-/- mice." (PMID 30469435, 2018). "It is therefore tempting to speculate that the effects on anemia and bone disease also could be due to increased BMP-6 or BMP-9 activity, due to activin A inhibition." (PMID 26047946, 2015). "The Bmp6 down-regulation observed in our Fpn1-deficient mice was not due to the effect of Tf-bound iron, anemia, or Epo expression." (PMID 24454764, 2014). "We first hypothesized that the decreased Bmp6 expression in our Fpn1 mouse models might be due to anemia and/or Epo." (PMID 24454764, 2014). "The proposed IL-6-ERRγ-BMP6 pathway is probably active in inflammatory conditions when pro-inflammatory cytokines, including IL-6, levels are increased and may up-regulate hepcidin expression, leading to hypoferremia and anemia, such as in inflammatory anemia." (PMID 32998264, 2020). "However, BMP6 is known to influence iron metabolism by inducing hepatic expression of the iron regulatory protein hepcidin, whose activity leads to reduced serum iron and, if chronically elevated, anaemia." (PMID 31586071, 2019). "Taken together, these suggest that while BMP6 is unlikely to be a major mediator of myeloma bone disease, it may contribute to the anaemia associated with multiple myeloma." (PMID 31586071, 2019). "Interestingly, in conditions of severe anemia, we also observed a decrease of bmp6 expression." (PMID 27100629, 2016). "Anti-BMP6 reagents attenuate intestinal inflammation in DSS-induced colitis mice and mitigate IBD anaemia." (PMID 37391444, 2023). "Due to the frequency of anemia in IBD and its clinical importance, this problem is worth further analysis and research projects, concerning both erythroferrone and BMP-6." (PMID 37755286, 2023). "An altered MT2 cannot appropriately suppress hepatic BMP6/SMAD signaling in case of low iron, hence hepcidin excess blocks dietary iron absorption, leading to a form of anemia resistant to oral iron supplementation." (PMID 34343368, 2021). "A blocking antibody to BMP6 did not have these effects on bone homeostasis, but did improve hepcidin-mediated anaemia." (PMID 31586071, 2019).
anemia (continued). "Evidence from experimental studies and our finding of low BMP6 in sepsis/septic shock patients indicate that blocking BMP6 pathways may not be an effective option for treating anemia in septic patients." (PMID 39200147, 2024). "Momelotinib acts by inhibiting the hyperactivated BMP6/ACVR1/SMAD pathway and suppressing hepcidin expression; thus, treatment with momelotinib results in higher circulating iron and Hb levels and improved erythropoiesis, which leads to significant anemia benefits in MF patients." (PMID 38201581, 2023). "Thus, we surmised that the decreased Hamp1 expression in Fpn1Alb/Alb mice was not due to the effects of anemia or increased Epo expression, but rather to decreased Bmp6 expression and/or decreased serum levels of Tf-bound iron." (PMID 24454764, 2014). "Moreover, Bmp6 was down-regulated under conditions of high iron demand, irrespective of the presence of anemia." (PMID 24454764, 2014). "Moreover, the expression of bone morphogenetic protein-6 (BMP-6), a secondary mediator of chronic inflammation anemia, did not exhibit any change, neither did the major iron carrying protein produced by the livers, transferrin." (PMID 24324805, 2013). "Anemia resulting from inflammatory processes has a high prevalence in critically ill patients; however, iron levels in SIRS and sepsis/septic shock patients were similar, indicating that iron does not contribute to the decline in BMP6 in sepsis/septic shock." (PMID 39200147, 2024).
hepatoma (19 papers, 2012 to 2025). "Treatment of hepatoma cells with 50 mm sodium chlorate caused a significant suppression of both unstimulated and BMP6-stimulated HAMP expression." (PMID 31315930, 2019). "In fact, BMP6 expression induced by iron has been found in mouse primary hepatocytes, human hepatocytes and human hepatocellular carcinoma." (PMID 39827450, 2025). "In the absence of TGFβ superfamily ligands, FKBP12 binds BMPR-I,36,69 decreasing their signaling, while high levels of BMP6 induce FKBP12 displacement from ALK2 receptor in hepatoma cells." (PMID 38052214, 2023). "We show herein that pharmacological iron chelation slightly impaired hepcidin induction by BMP6 and/or IL-6 primarily in human Huh7 hepatoma cells." (PMID 34161397, 2021). "Treatment of hepatoma cells or primary murine hepatocytes with BMP6, BMP2 or IL-6 recapitulates hepcidin induction." (PMID 34161397, 2021). "Quantitative real-time PCR, chromatin immunoprecipitation and glucose output assays were used to assess BMP6 effect on gluconeogenesis in rat hepatoma H4IIE cells." (PMID 30539233, 2019). "The effect of factors known to regulate TMPRSS6 expression, such as IL‐6, LPS and BMP‐6,39, 42 should be taken into consideration in human hepatoma cell lines, but also in mice to see if they affect expression levels of specific TMPRSS6 isoforms." (PMID 29441715, 2018). "We have previously demonstrated that heparins have a strong anti-hepcidin activity, both in vitro in hepatoma cells and in vivo in mice, and that they act by interfering with the BMP6/SMAD pathway." (PMID 27711215, 2016). "In addition, according to the reported important role of BMP6 in hepcidin regulation, we next directly treated human hepatoma cells Huh7 with recombinant human BMP6 protein." (PMID 34740612, 2021). "BMP2 and BMP6 regulate hepatocellular carcinoma progression and prognosis." (PMID 26029998, 2015). "Even though several other BMPs, including BMP2, 4, 5, 7 and 9, all robustly induce hepcidin expression in primary hepatocytes or hepatoma cell lines, and their mRNAs are also detected predominantly in the NPCs of rat liver, they cannot compensate the function of BMP6 in Bmp6-/- mice." (PMID 23565256, 2013). "Since similar effect regarding BMP6 secretion upon APAP stimuli was found in mouse hepatocytes and in the human hepatoma cell line Huh7, we used Huh7 cells for further experiments." (PMID 39827450, 2025). "As expected, BMP6 and BMP2 treatment, alone or in combination, induced HAMP mRNA in human Huh7 hepatoma cells." (PMID 36982241, 2023). "PB treatment of hepatocyte-derived Huh7 hepatoma cells increased HAMP expression at baseline and also potentiated the increase of HAMP produced by exogenous recombinant BMP6." (PMID 28864822, 2017). "We performed co-stimulation experiments with BMP6 and IL6 in human hepatoma (HuH7) cells, and measured the activity of a luciferase reporter gene driven by the hepcidin promoter 24 h after stimulation." (PMID 24391488, 2014). "To understand the mechanism of BMP6 action, we studied its effect in H4IIE rat hepatoma cell line." (PMID 30539233, 2019).
iron overload (15 papers, 2011 to 2025). "Of note, also deficiency of the BMP ligands Bmp2 and Bmp6 in liver sinusoidal endothelial cells leads to severe iron overload." (PMID 39545682, 2024). "Bone loss has been reported frequently in HH patients as well as in some mouse models of iron overload, including Hfe−/− mice, Bmp6−/− mice, and hepcidin‐deficient mice, although with controvertial results." (PMID 39545682, 2024). "A recent report proposes that variants in the pro-peptide region of BMP6 are the underlying cause of several cases of iron overload." (PMID 29695288, 2018). "A recent report associated heterozygosity for three variants p.P95S, p.L96P, and p.Q113E in the BMP6 pro-peptide region with nine clinical cases of unexplained atypical iron overload." (PMID 29695288, 2018). "Our data suggest that assignment of disease causation in clinical cases of iron overload to pro-peptide variants in BMP6 should thus be treated with caution and requires biological characterization." (PMID 29695288, 2018). "We also found exonic non-synonymous variants in BMP6, HP and Serpina1, whose proteins might act as possible modulators of hepcidin synthesis and iron overload." (PMID 33513852, 2021). "Experimental inactivation of BMP6 causes serious iron-overload, while recent evidence suggests that BMP6 mutations could be the source of a mild but still unrecognized form of hemochromatosis (HH)." (PMID 30134796, 2018). "Global disruption of Bmp6 in mice reduces hepcidin expression and causes severe iron overload." (PMID 23565256, 2013). "Both BMP5 and BMP6 are strong regulators of hepcidin expression, and the hepcidin levels cannot be increased in BMP5 and BMP6 double-deficient mice as response to iron overload." (PMID 39965404, 2025). "BMP6-KO mice have low levels of pSMAD1/5/8 despite severe iron overload, and their hepcidin expression is markedly reduced." (PMID 34740612, 2021). "Here, we report on three clinical cases of unexplained atypical iron overload carrying an amino acid insertion within the same region of the BMP6 pro-peptide." (PMID 29695288, 2018). "The so-called ‘toxic iron’ and not iron itself is the factor initiating BMP6-driven hepcidin synthesis and a distinction should be made between iron accumulation that is tolerated, and the development of pathogenic iron overload." (PMID 40149659, 2025). "By contrast, expression of BMP6 was appropriately elevated in HFE HH in relation to iron overload." (PMID 40149659, 2025). "Furthermore, heterozygous mutations affecting the BMP6 propeptide have been associated with an inappropriate reduction in hepcidin levels and mild iron overload in some but not all populations." (PMID 37179448, 2023). "Second, Fpn inactivation in HCs, macrophages and duodenum, that leads to liver iron overload and decreases serum iron and TS, does not increase, but even down-regulate, liver Bmp6 expression." (PMID 25860887, 2015). "Bmp6, a member of the transforming growth factor-beta (TFG-β) superfamily seems to be the major ligand that activates hepcidin levels, because Bmp6 knock-out mice show severe iron overload due to a failure to activate hepcidin expression." (PMID 23917168, 2013).
iron deficiency (13 papers, 2012 to 2025). "Hepatic hepcidin expression was reduced, as well as one of its major regulators, BMP6, as a result of the iron deficiency." (PMID 39869503, 2025). "Altogether, Agt-KO responds to iron deficiency by decreasing liver hepcidin production via the canonical BMP6 pathway." (PMID 39869503, 2025). "On the other hand, the level of the BMP6 protein is reduced in the iron deficiency state, reducing the hepcidin expression by preventing the HJV-BMP6-SMAD4 pathway." (PMID 35163110, 2022). "The HJV-BMP6-SMAD signaling pathway that normally activates the expression of hepcidin in iron deficiency is impaired by vitamin A deficiency despite increased expression of liver Bmp6 and Hfe2 mRNA levels and decreased expression of Smad7 mRNA." (PMID 27551308, 2016). "Transcription of Bmp6 is suppressed in iron deficiency and upregulated in iron overload; this regulation is liver specific and no other tissue modulates Bmp6 in response to iron, in agreement with the central role of the liver in iron homeostasis." (PMID 25860887, 2015). "Both KCs and LSECs upregulated Bmp6 expression in dietary iron overload, while the opposite occurred in iron deficiency." (PMID 25860887, 2015). "In contrast, Tmprss6-/- mice with an inappropriately high hepcidin expression and iron deficiency have increased BMP signaling but decreased Bmp6 expression in the liver." (PMID 23565256, 2013). "Liver Hamp mRNA, Bmp6 mRNA and Id1 mRNA displayed the expected response to iron overload and iron deficiency." (PMID 22629388, 2012). "However, the magnitude of the effect of iron deficiency on these genes is dissimilar, such that Hamp1 indexed to Bmp6 is markedly less in the ID mice compared to control, and decreased further in the IDA mice." (PMID 35634155, 2022). "We speculate that in the setting of iron deficiency an increase in the concentration of circulating holoTf, relative to unsaturated Tf form(s), enhances hepatocellular BMP6 sensitivity." (PMID 35634155, 2022). "In conclusion, this study demonstrates that the HJV-BMP6-SMAD signaling pathway that normally activates the expression of hepcidin in iron deficiency is impaired by vitamin A deficiency despite increased expression of liver Bmp6 and Hfe2 mRNA levels and decreased expression of Smad7 mRNA." (PMID 27551308, 2016). "The tissue and systemic iron deficiency of FeD rats may have led to the lower levels of hepatic Bmp6 mRNA and consequent strong down-regulation of Hamp mRNA levels compared to those of the control group." (PMID 27551308, 2016). "In conditions of iron deficiency, increased TMPRSS6 protein content could thus result in decreased activity of the BMP6/HFE2 signaling pathway, contributing to the well-documented decrease of Hamp expression." (PMID 26845567, 2016).
myeloma (11 papers, 2005 to 2025). "Consistent with this, we found treatment of human JJN-3 and murine 5TGM1 myeloma cells with recombinant human BMP6 induced a dose-dependent reduction in myeloma cell viability that was rescued in both cell lines by treatment with LDN." (PMID 31586071, 2019). "Consistent with this, liver hepcidin (Hamp1) expression and serum hepcidin concentrations were reduced in anti-BMP6-treated myeloma-bearing mice, and serum iron and haemoglobin concentrations were increased." (PMID 31586071, 2019). "This appears to be counterproductive, as BMP6 can more strongly induce apoptosis in primary myeloma cells via the type I receptor ACVRI (ALK2) as BMP2 and -4 can do via the BMPRIA and/or -IB." (PMID 28489849, 2017). "In myeloma cells, BMP-6- and BMP-9-induced activation of SMAD1/5/8 through ACVR2A/ACVR2B/ALK2 was inhibited by activin A treatment." (PMID 26047946, 2015). "Nevertheless, in multiple myeloma BMP6 was found to protect cells against bortezomib-induced apoptosis." (PMID 24069261, 2013). "Thus, in addition to osteogenic differentiation and disrupting stromal support for MM, BMP2 and BMP6 exert direct anti-myeloma effects and inhibit IL6-mediated proliferation." (PMID 41463400, 2025). "Furthermore, ACVR1/ALK2 is -in contrast to BMPRIA and -IB- ubiquitously expressed in myeloma cells, which potentially renders BMP6 a more versatile Activin A antagonist than BMP2." (PMID 28489849, 2017). "Having established that FK506 potentiated BMP6-induced SMAD1/5/8-activation and apoptosis in INA-6 cells, we next wanted to see how common this was among myeloma cell lines." (PMID 36717825, 2023). "Using myeloma cell lines with well-characterized BMP-receptor expression and responses, we found that activin A inhibited signaling by BMP-6 and BMP-9 by competing for type 2 receptors." (PMID 26047946, 2015). "Similar effects as demonstrated for BMP-6 on human B cells in the present study, were demonstrated for BMP-2, 4, 6 and -7 in human myeloma cells." (PMID 15877825, 2005). "In addition to the indirect effect via the microenvironment, we also investigated the direct anti-myeloma potential of BMP2 and BMP6." (PMID 41463400, 2025). "Given the key role of IL6 in supporting MM survival and proliferation, and our observation that BMP2 and BMP6 reduced IL6 expression in MSCs, we next assessed whether they could directly counteract IL6-induced myeloma growth." (PMID 41463400, 2025). "Thus, the ratio between follistatin and activin A should determine activin A’s ability to inhibit BMP-6 or BMP-9, both with regards to myeloma cell apoptosis and to osteoblastogenesis." (PMID 26047946, 2015). "Using myeloma cell lines as a model system, we show that activin A antagonizes BMP-6 or BMP-9-signaling through ACVR2A/ACVR2B/ALK2, but not BMP-2 or BMP-4-signaling through BMPR2/ALK3 or BMPR2/ALK6." (PMID 26047946, 2015). "Thus, ALK2, ACVR2A and ACVR2B are candidate mediators of the antagonizing effects of activin A on BMP-6 and BMP-9 signaling in myeloma cells." (PMID 26047946, 2015). "However, BMP6-mediated inhibition of 5TGM1 myeloma cell growth was also prevented by co-culture with HS5 bone marrow stromal cells in the absence of LDN, suggesting that the microenvironment may also mediate the response of myeloma cells to BMP signalling." (PMID 31586071, 2019). "BMP-6 and BMP-9 signals through the type 1 receptor ALK2 in myeloma cells, whereas BMP-2 and BMP-4 do not signal in cells that express ALK2, but lack ALK3 and ALK6, as is the case for the INA-6 myeloma cell line." (PMID 26047946, 2015). "The main finding reported here is that activin A, by sharing receptors with BMP-6 and BMP-9, but not BMP-2 and BMP-4, may inhibit BMP-6 and BMP-9-induced apoptosis in myeloma cells." (PMID 26047946, 2015).